NOTCH1 (notch receptor 1)
Description:
Functions as a receptor for membrane-bound ligands Jagged-1 (JAG1), Jagged-2 (JAG2) and Delta-1 (DLL1) to regulate cell-fate determination. Upon ligand activation through the released notch intracellular domain (NICD) it forms a transcriptional activator complex with RBPJ/RBPSUH and activates genes of the enhancer of split locus. Affects the implementation of differentiation, proliferation and apoptotic programs. Involved in angiogenesis; negatively regulates endothelial cell proliferation and migration and angiogenic sprouting. Involved in the maturation of both CD4(+) and CD8(+) cells in the thymus. Important for follicular differentiation and possibly cell fate selection within the follicle. During cerebellar development, functions as a receptor for neuronal DNER and is involved in the differentiation of Bergmann glia. Represses neuronal and myogenic differentiation. May play an essential role in postimplantation development, probably in some aspect of cell specification and/or differentiation. May be involved in mesoderm development, somite formation and neurogenesis. May enhance HIF1A function by sequestering HIF1AN away from HIF1A. Required for the THBS4 function in regulating protective astrogenesis from the subventricular zone (SVZ) niche after injury. Involved in determination of left/right symmetry by modulating the balance between motile and immotile (sensory) cilia at the left-right organiser (LRO).
Synonyms: hN1; TAN1; AOS5; AOVD1
Tractability: Small molecule: a structure with a bound ligand is known; a high-quality ligand is known; it has a binding pocket of medium quality; it belongs to a druggable protein family. Antibody: a drug acting on it is in phase 2 or 3 trials; its Gene Ontology location is reachable by antibodies, with high confidence; UniProt places it where antibodies can reach, with medium confidence; UniProt predicts a signal peptide or a membrane-spanning region. PROTAC: UniProt records ubiquitination sites on it; ubiquitination databases record sites on it; its protein half-life has been measured; a small molecule that binds it is known.
Target class: Membrane receptor
Gene: Protein-coding gene on chromosome 9 (136,494,433 to 136,546,048, reverse strand). Ensembl gene ENSG00000148400.
Subcellular location: Cell membrane; Late endosome membrane; Nucleus (Notch 1 intracellular domain)
Subcellular location (Human Protein Atlas): Nucleoplasm
Pathways (Reactome):
Disease: Constitutive Signaling by NOTCH1 HD Domain Mutants; Constitutive Signaling by NOTCH1 HD+PEST Domain Mutants; Constitutive Signaling by NOTCH1 PEST Domain Mutants; Constitutive Signaling by NOTCH1 t(7;9)(NOTCH1:M1580_K2555) Translocation Mutant; Defective LFNG causes SCDO3; Loss of Function of FBXW7 in Cancer and NOTCH1 Signaling; Nuclear events stimulated by ALK signaling in cancer
Signal Transduction: Activated NOTCH1 Transmits Signal to the Nucleus; NOTCH1 Intracellular Domain Regulates Transcription; NOTCH3 Intracellular Domain Regulates Transcription; NOTCH4 Intracellular Domain Regulates Transcription; Pre-NOTCH Processing in Golgi; Pre-NOTCH Processing in the Endoplasmic Reticulum; Pre-NOTCH Transcription and Translation
Developmental Biology: Differentiation of naive CD4+ T cells to T helper 2 cells (Th2 cells); Formation of paraxial mesoderm; Regulation of gene expression in late stage (branching morphogenesis) pancreatic bud precursor cells; Somitogenesis
Gene expression (Transcription): Notch-HLH transcription pathway; RUNX3 regulates NOTCH signaling
Cellular responses to stimuli: NFE2L2 regulating tumorigenic genes; Regulation of NFE2L2 gene expression
Gene Ontology:
Molecular function: identical protein binding; protein binding; transcription coactivator activity; transmembrane signaling receptor activity; enzyme binding; enzyme inhibitor activity; calcium ion binding; chromatin binding; chromatin DNA binding; Notch binding; signaling receptor activity; transcription regulator activator activity
Biological process: aortic valve morphogenesis; cellular response to follicle-stimulating hormone stimulus; cellular response to tumor cell; cellular response to vascular endothelial growth factor stimulus; epithelial to mesenchymal transition; heart development; mitral valve formation; negative regulation of anoikis; negative regulation of cell adhesion molecule production; negative regulation of cell migration involved in sprouting angiogenesis; negative regulation of cell population proliferation; negative regulation of cell-cell adhesion mediated by cadherin; negative regulation of cell-substrate adhesion; negative regulation of endothelial cell chemotaxis; negative regulation of gene expression; negative regulation of myoblast differentiation; negative regulation of stem cell differentiation; negative regulation of transcription by RNA polymerase II; neuronal stem cell population maintenance; Notch signaling pathway; outflow tract morphogenesis; positive regulation of cell population proliferation; positive regulation of DNA-templated transcription; positive regulation of ERK1 and ERK2 cascade; positive regulation of Ras protein signal transduction; and 102 more
Cellular component: CSL-Notch-Mastermind transcription factor complex; late endosome membrane; MAML1-RBP-Jkappa- ICN1 complex; nucleus; receptor complex; adherens junction; apical plasma membrane; cell surface; cytosol; endoplasmic reticulum membrane; endosome membrane; extracellular region; Golgi membrane; nucleoplasm; plasma membrane; acrosomal vesicle; cell periphery; cytoplasm; cytoplasmic vesicle; endoplasmic reticulum; glutamatergic synapse; membrane; postsynaptic density membrane; Schaffer collateral - CA1 synapse
Genetic constraint (gnomAD): Loss-of-function variants: 36 observed, 219.47 expected, observed/expected ratio (o/e) 0.16, 90% interval 0.12 to 0.22. The upper end of that interval is the gene's LOEUF score, 0.22, which puts it in group 1 of 6, group 1 being the genes least tolerant of losing a copy. Missense variants: 2,971 observed, 3,576.3 expected, observed/expected ratio (o/e) 0.83, 90% interval 0.81 to 0.86. Synonymous variants: 1,731 observed, 1,557 expected, observed/expected ratio (o/e) 1.11, 90% interval 1.07 to 1.16.
Cancer hallmarks: proliferative signalling (promotes); escaping programmed cell death (promotes); change of cellular energetics (promotes); angiogenesis (promotes); cell replicative immortality (promotes)
Homologues: Orthologues: chimpanzee NOTCH1 (99% identical), macaque NOTCH1 (99% identical), mouse Notch1 (91% identical), rat Notch1 (91% identical), dog NOTCH1 (90% identical), pig NOTCH1 (90% identical), guinea pig NOTCH1 (85% identical), tropical clawed frog notch1 (74% identical), zebrafish notch1b (69% identical), zebrafish notch1a (67% identical). Paralogues in human: NOTCH2 (53% identical), NOTCH3 (48% identical), SNED1 (15% identical), NOTCH2NLR (5% identical), NOTCH2NLC (4% identical), NOTCH2NLB (4% identical), NOTCH2NLA (4% identical).
Diseases named in the same sentence as NOTCH1 in open-access papers:
NOTCH1 is named in the same sentence as 659 diseases in open-access papers, as found by Europe PMC text mining. Sharing a sentence is not in itself a finding about the gene and the disease. The quoted sentences say what the papers report.
breast cancer (500 papers, 2005 to 2026). A primary or metastatic malignant neoplasm involving the breast. "Notch1 mutations have been implicated in the progression of various cancer types, including breast cancer, leukemias, HNSCC, and squamous cancers of the skin, esophagus, cervix, and lung." (PMID 41026775, 2025). "It has been shown that higher NOTCH1 mRNA expression is associated with decreased paclitaxel effect in breast cancer cell lines or doxorubicin resistance in small-cell lung cancer cells." (PMID 39153127, 2025). "Activation of Notch1, among other Notch family proteins, has been shown to cause mammary carcinomas in mice." (PMID 39330508, 2024). "Here, we have crossed conditional knockout Notch1 or Notch2 alleles into an established mouse mammary tumour model." (PMID 37686600, 2023). "Increased Notch1-IC expression causes Adriamycin resistance in breast cancer cells, yet this process can be dramatically reversed by FBXW7 promoting proteasomal degradation of Notch1." (PMID 37658431, 2023). "YAP1 expression was positively correlated with Notch1 in breast cancer, and CCL5/CCR5 activated YAP in tumor-associated macrophages." (PMID 37759462, 2023). "NOTCH1 is associated with numerous signaling pathways in tumorigenesis, and it is involved in many types of cancer, including brain tumors, leukemia, breast cancer, and several other cancer types." (PMID 37671046, 2023). "In preclinical models of breast cancer, NOTCH1 signaling pathway activation has been associated with an increased risk of brain metastases." (PMID 36980614, 2023). "Estrogen deprivation or tamoxifen cause activation of Notch1 in ER-positive breast cancer cells, and Notch inhibition dramatically increased the efficacy of tamoxifen in MCF-7 xenografts, causing tumor regression." (PMID 37568775, 2023). "Nonetheless, it is reported that there are SEC16A‐NOTCH1 fusions in breast cancer, causing NOTCH1 signaling." (PMID 37321964, 2023). "Through targeting Bcl-2, CD44, and SIRT1 (silent information regulator 1), Rac1, Fra-1, Notch-1, and different cyclins, exogenous expression of miR-34a in breast cancer cells caused cell death and decreased cell proliferation and migration." (PMID 36325275, 2022). "Analysis of The Cancer Genome Atlas (TCGA) database found that activated Notch1 is reportedly mutated in approximately 13% of TNBCs, is strongly enriched in the basal subtype, and is positively correlated with breast cancer progression." (PMID 35186194, 2022). "In patients with trastuzumab-resistant and HER2+ breast cancer, Notch1 expression was associated with poorer prognosis." (PMID 36046046, 2022). "The inhibition of Notch1 caused growth arrest and inhibition of epithelial to mesenchymal transition in breast cancer stem cells." (PMID 36017236, 2022). "A meta-analysis of tumor molecular landscapes and several pathological studies have shown that Notch1 activity is associated with the risk of recurrence in ER+ breast cancer." (PMID 36046046, 2022). "In estrogen receptor-positive (ER +) breast cancers, NOTCH1 activity is correlated with the risk of tumor recurrence." (PMID 36517618, 2022). "In breast cancer, doxorubicin upregulated the Notch1/multidrug-resistance-associated protein-1 (MRP1) axis, thus reducing the effective intracellular concentration of the cytotoxic agent." (PMID 34680255, 2021). "Although mutation of NOTCH1 or NOTCH2 only occurs in a small proportion of breast cancer cases, inclusion of cases harboring both mutation and overexpression accounts for 30% of poor-prognosis TNBC cases." (PMID 33750924, 2021). "In human breast cancer, elevated expression of Jagged1 (and Notch1) is associated with osteolytic bone metastasis and poor prognosis." (PMID 34680255, 2021).
breast cancer (continued). "High expression of Notch1 and Jag1 is associated with poor overall survival (OS) in breast cancer, suggesting the importance of this signaling axis in human breast cancer." (PMID 34911937, 2021). "In close to 10,000 breast cancer samples (using default settings to avoid multiple testing, thus including a heterogeneous cohort of all breast cancer patients available), notch-1 and notch-3 expression was positively associated with MSI-1." (PMID 34291358, 2021). "The high expressions of Notch-1 and Jagged-1 are associated with poor prognosis of breast cancer and promote the transformation of breast epithelial cells." (PMID 34872446, 2021). "Adenoid cystic carcinoma and breast cancer also contain point mutations or deletions in the Notch1 gene, resulting in the constitutive production of the cleaved, active intracellular form." (PMID 32796631, 2020). "Several studies have shown that Notch 1 and Jagged-1 expression are negatively associated with prognosis in breast cancer." (PMID 32575680, 2020). "It is revealed that loss of the two main regulators of asymmetric cell division, MSI1 and Notch1, in these cells causes creation of ERα/PR+ breast cancer." (PMID 32448364, 2020). "In the present study, our data clearly demonstrate that expression of ICN1, representing Notch1 activation, promotes Brca1-associated mammary tumour formation." (PMID 32591500, 2020). "In support of this, overexpression of Notch 1 and Jagged-1 was also associated with poor prognosis for all types of breast cancer, including HER2+ cancer." (PMID 32575680, 2020). "In 54 BRCA1-deficient breast cancers in this cohort, increased expression of NOTCH1 also correlated with TNBC and the basal-type." (PMID 32591500, 2020). "NOTCH1 expression has also been implicated in cancer cell metastasis, and breast cancer patients positive for NOTCH1 have experienced shorter disease-free survival." (PMID 32093026, 2020). "It is in accordance with our finding that a previous research has also verified that ICAM-1 was implicated in Notch-1 signaling pathway in breast cancer." (PMID 31343412, 2019). "EZH2 can activate NF-κB targets and NOTCH1 in breast cancer cells, which has also been implicated in the transcriptional activation of gene expression in breast cancer." (PMID 30881302, 2019). "Parr and colleagues analyzed Notch-1 and Notch-2 mRNA and protein expression levels in normal and breast cancer tissues also in association whit clinicopathological parameters." (PMID 31379945, 2019). "In particular, the Notch1 gene was identified as a novel target for mouse mammary tumor virus (MMTV) insertional activation, thus leading to the overexpression of Notch1 mutated forms, finally involved in mammary tumor formation." (PMID 31379945, 2019). "Earlier studies in breast cancer reported that high expression levels of Notch1 and Jag1 were associated with poor prognosis, suggesting a possible interplay between estrogen and the Notch signaling pathway." (PMID 29996493, 2018). "In Ductal Carcinoma in situ (DCIS), Notch1 signaling is active and associated with the development of breast cancer." (PMID 30515368, 2018). "Pathway and network analysis revealed that altered Notch1 signaling occurred in ER+/PR+/HER2+/− breast cancers, whereby Notch1 mutations are more prevalent in HER2− than HER2+ tumors." (PMID 30515368, 2018). "Results from a Meta–analysis involving 3867 patients showed that Notch1 expression positively correlates with breast cancer progression and that higher expression is associated with a transition from ductal carcinoma in situ to invasive cancer." (PMID 30515368, 2018). "High expression of Notch1 and Jagged1 in breast cancer is linked to poor survival rates, and Jagged 1 is highly expressed in metastatic prostate cancer as compared to localized or benign prostatic tissue." (PMID 28030808, 2017).
breast cancer (continued). "In the search for mechanistic clues of the CCR7-mediated augmentation of the mammary stem cell compartment, we investigated crosstalk between CCR7 and Notch1 pathways, as Notch1 signaling has also been implicated in mammary cancer stem cells." (PMID 28137279, 2017). "High Notch1 level has been linked to poor prognosis in breast cancer, where Notch1 has been shown to induce EMT." (PMID 27705934, 2017). "For example, elevated expression of Jagged1 and Notch1 has been linked to poor prognosis in breast cancer patients." (PMID 26880941, 2016). "Reports have showed that high level expression of NOTCH1 was associated with poor survival in primary breast cancer-diagnosed patients." (PMID 28330128, 2016). "Notch1 signaling is aberrantly activated in breast cancer, and increased expression of the Notch1 intracellular domain (Notch1-IC) is associated with low survival rates in various cancers, including breast cancer." (PMID 27806347, 2016). "Αn opposite effect has been described in breast cancer cells where HER-2 inhibition using transtuzumab caused increased Notch 1 activity." (PMID 26497899, 2015). "NOTCH1 is involved in many cellular signaling processes associated with development and cell fate and has recently been suggested to be a novel oncogene in breast cancer." (PMID 25729435, 2015). "Ultimately, we evaluated the association between Notch1 expression level and survival outcome of breast cancer patients." (PMID 26121683, 2015). "We found a positive association between Notch1 signaling and breast cancer invasion and progression, thus presenting a potential oncogenic role." (PMID 25645291, 2015). "Notch molecules are a family of four (Notch1 to 4) signalling molecules that can act as transcriptional co-regulators; Notch1 is implicated in mammary gland development, breast cancer and chemoresistance to doxorubicin." (PMID 26362310, 2015). "This meta-analysis suggests that Notch1 is an important indicator of progression and is associated with prognosis, especially in the basal type of breast cancers." (PMID 26121683, 2015). "Notch1 has been shown to be overexpressed in breast cancer, and its expression levels have been associated with breast cancer prognosis." (PMID 23990015, 2014). "Increased co-expression of Notch-1 and Jagged-1 has been associated with poor prognosis for women diagnosed with breast cancer." (PMID 25566499, 2014). "Higher expression of Notch-1 and its ligand Jagged-1 is associated with poor prognosis in breast cancer." (PMID 24914410, 2014). "Multiple lines of evidence suggest that Notch signaling is involved in breast cancer development, maintenance and metastasis, and overexpression of Notch-1, -3, and -4 activated intracellular domains in mice causes aggressive and metastatic mammary tumors." (PMID 25309874, 2014). "This likely occurs in breast cancer, where NOTCH1 or FBXW7 manifest low mutational rates and where, instead, high levels of Pin1 are frequent and strongly correlate with activated N1-ICD." (PMID 24357640, 2014). "Both immunohistochemistry and real-time PCR experiments demonstrated a strong association of ALDH1 with the reversed NOTCH1 expression in breast cancer." (PMID 23767668, 2013). "Specifically, high-level expression of Jagged-1, Notch-1 and Notch-2 has been found to be associated with poor overall survival in human breast cancer." (PMID 22949821, 2012). "Notch1 transactivation of Myc has also been implicated in the pathogenesis of other neoplasms, including murine mammary tumors." (PMID 22022427, 2011). "For example, co-expression of Notch1 and Jag1 has been associated with poor outcomes in patients with breast cancer." (PMID 20161710, 2010). "Co-expression of high levels of Jagged1 and Notch1 was associated with poor survival in breast cancers." (PMID 20030805, 2009).